MDK (midkine)
Diseases named in the same sentence as MDK in open-access papers (continued):
Sharing a sentence is not in itself a finding about the gene and the disease.
tumor (continued). "Further analysis showed that ligand-receptor pairs, including MIF − (CD74 + CXCR4), MIF − (CD74 + CD44), MDK–NCL and LGALS9 − CD45, etc. mediated the communication between m6A associated subtypes of TME cells and tumor epithelial cells." (PMID 35509079, 2022). "Surgery resulted in a progressive reduction in systemic Vegfr3Luc emission, consistent with the need for tumor‐driven MDK secretion to activate premetastatic niches." (PMID 34762341, 2021). "The pathway analysis showed the involvement of the selected proteins in biological processes directly associated with tumor evolution (SEMA3A, BMP6, MDK), hepatitis viral infection (ISG15), or physiological liver functions (PLTP)." (PMID 35008303, 2021). "MDK (Midkine), a heparin-binding growth factor, is abnormally overexpressed in several human malignancies playing a key role during tumor development." (PMID 33800494, 2021). "Mechanistically, we found these dsRNA polyplexes to act by dual transcriptional inhibition of MDK and VEGFR3 in both tumor cells and their associated activated lymphatic vasculature, respectively." (PMID 34762341, 2021). "MDK is a heparin-binding growth factor that is expressed at abnormally high levels in various cancers, especially during tumour progression into more advanced stages." (PMID 34759262, 2021). "Together, these data illustrate the versatility of Vegfr3Luc reporters to discover new mechanisms of action of anticancer agents, including repressors of tumor‐driven MDK." (PMID 34762341, 2021). "MDK is expressed in a variety of tumor types, but it had not been pharmacologically targeted to prevent lymphovascular premetastatic niche activation." (PMID 34762341, 2021). "Though this study provides a solid theoretical basis for the treatment of GBM, the role of MDK in tumor progression in vivo is complex and needs further exploration." (PMID 34556138, 2021). "Serum-Midkine (S-MK) has already been proposed as a potential biomarker for different tumor entities including gastrointestinal and lung cancer." (PMID 34272441, 2021). "Elevated MDK level has been observed both in the tumor tissue and in the blood samples of HCC patients." (PMID 33562077, 2021). "The MDK-expression group also showed a significantly higher pro-tumor effect and metastasis than the control group, which was abrogated by iMDK treatment." (PMID 32847073, 2020). "Of note, the tumor growth-promoting activity of MDK is also partially due to its ability to promote tumor angiogenesis as a potent proangiogenic factor." (PMID 32847073, 2020). "This study aimed to investigate a larger collective to ascertain if the preoperative serum midkine level (S‐MK) is suitable as a marker for screening and if S‐MK correlates with tumor progression and localization." (PMID 31984657, 2020). "On the other hand, the MDK+iMDK treatment group displayed greater effects of anti-tumor and -metastasis compared with the MDK-expression group and showed 60% survival rates until termination of the experiment at 100 days." (PMID 32847073, 2020). "An increased tumor burden and metastatic secondary tumors in the MDK-expression group was also reflected by photon emission values of each mouse compared with the control and MDK+iMDK treatment." (PMID 32847073, 2020). "IGFBP7 and MDK expressed by tumor cells and CAFs promote tumor progression and relapse by enhancing cancer stemness, EMT, extracellular matrix remodeling, and angiogenic activity." (PMID 32460812, 2020). "In an in vivo lung orthotopic model, MDK-induced tumor progression decreased due to a decrease in CD-31 and NF-κB expression in response to iMDK treatment." (PMID 32847073, 2020). "Tumor volume and tumor weight in cells expressing MDK were almost twice as high as the control group." (PMID 32847073, 2020). "The tumor volume of the stably overexpressed MDK group began to grow bigger than that of the control group treated with DMSO from around 40 days." (PMID 32847073, 2020).
tumor (continued). "Antagonizing MDK reduced the survival of GBM tumor spheres through the promotion of cell cycle arrest and the consequent apoptotic cell death caused by oxidative stress-induced DNA damage." (PMID 31811117, 2019). "A549 carrier cells infected with AdE3‐midkine or co‐infected with AdE3‐midkine and Ad‐mGM‐CSF induced 30% or 60% of complete tumor reduction, respectively (p < 0.05)." (PMID 30548997, 2019). "We identified several genes that were significantly correlated with sensitivity to anti-MDK therapy in GBM tumor spheres using elastic net analysis." (PMID 31811117, 2019). "Here, through a liquid chromatography-mass spectrometry (LC-MS)-based secretome analysis, we identified midkine (MDK) as an autocrine factor in patient-derived GBM tumor spheres." (PMID 31811117, 2019). "Recent studies revealed that MDK contributes to tumor metastasis via the lymphatic vessels through systemic induction of neo-lymphangiogenesis." (PMID 31811117, 2019). "Under serum-induced differentiation conditions, the expression level of MDK was notably decreased in three different tumor spheres." (PMID 31811117, 2019). "Serum and plasma levels of MDK are evidently correlated with diagnosis and prognosis in cancer patients (higher MDK level usually suggests tumor occurrence and worse prognosis)." (PMID 29872508, 2018). "Univariate analysis of our patients’ data found LVI, T stage III-IV, AJCC tumor stage III-IV and positive midkine expression to be associated with poorer disease free and overall survival." (PMID 29486735, 2018). "Recently, midkine, a heparin-binding factor produced by tumor cells, was identified as a critical factor for mTOR-dependent lymphangiogenesis in premetastatic sites including skin, LN, spleen, and lung." (PMID 29527513, 2018). "We quantified both gene products in our data, both significantly elevated in tumor relative to control (MDK T/C 13.55; HAI1 T/C 2.18, q<0.10)." (PMID 30419021, 2018). "In tumors, MDK can promote tumor cells differentiation, proliferation, anti-apoptosis, chemoresistance, transformation and epithelial-mesenchymal transition (EMT)." (PMID 29872508, 2018). "MDK is generally highly expressed in diverse malignant solid tumors, and enhances the tumor cells survival, migration, tumor angiogenesis and chemotherapy resistance." (PMID 29872508, 2018). "Compared with other measuring methods, IHC is more economic and easier to be spread for the detection of MDK in tumor tissues." (PMID 29872508, 2018). "Our analysis revealed for the first time that MGUS is characteristic by low levels of TGFB1 and high levels of midkine, a heparin-binding growth factor involved in angiogenic and anti-apoptotic functions and tumor expansion in various cancers." (PMID 29050213, 2017). "Midkine expression is also linked to inflammatory reactions, which can contribute to elevated midkine levels in non-tumorous pleural diseases." (PMID 28335760, 2017). "This midkine-trap blocked the internalization of the growth factor and its translocation to nucleus and prevented tumor cells growth." (PMID 28306378, 2017). "Representative IHC results are presented to show tumor specimens with different levels of midkine expression." (PMID 27974680, 2016). "Various cancers express significantly higher levels of the midkine protein in early stage tumor tissues than in adjacent normal tissues." (PMID 27974680, 2016). "Midkine was reported to be a key molecule in carcinogenesis, angiogenesis, tumor growth and anti-apoptotic signaling." (PMID 27974680, 2016). "Serum MDK was also superior to AFP in the diagnosis of NASH-HCC and was associated with more aggressive tumour clinicopathological features." (PMID 27219517, 2016). "In our study, we observed significant correlations between the serum concentrations and tumor tissue expression of midkine." (PMID 27974680, 2016). "A significant association was observed between the serum midkine levels and midkine immunoreactivity in tumor tissues." (PMID 27974680, 2016).
tumor (continued). "The serum midkine levels in 153 patients with NSCLC, 23 patients with benign pulmonary diseases and 95 healthy controls were analyzed using an ELISA to investigate the role of midkine as a tumor marker for NSCLC." (PMID 27974680, 2016). "Midkine expression in tumor tissues from 33 patients with HNSCC who underwent definitive surgical resection without preoperative treatment was examined by immunohistochemistry." (PMID 26798989, 2016). "It is plausible therefore that early in NAFLD-HCC pathogenesis, MDK has increased expression in tumour tissue or that MDK expression in adipocytes contributes directly to tumour development." (PMID 27219517, 2016). "MDK is also an angiogenic factor that enhances endothelial proliferation and increases tumor vascular density." (PMID 23991127, 2013). "Communication between drug-resistant cells by secretion of survival factors, such as midkine, is postulated to protect cells in the surrounding environment and enable survival of the tumor as a whole." (PMID 24083030, 2013). "To further determine the effectiveness and specificity of iMDK in suppressing MDK-expressing tumor cells, we treated both MDK-positive and MDK-negative cells with iMDK and assessed cell viability." (PMID 23976985, 2013). "In the present study, we have identified a small molecule compound iMDK that inhibits the expression of MDK, a tumor-promoting growth factor." (PMID 23976985, 2013). "These included genes known to be expressed by microglia (CCL8, SPP1, IRF7, IL1RAP), macrophages (IL1RN, SPP1, PDPN, IL1RAP, MDK, TFRC, HRH4), and tumor-associated macrophages (IL6, SPP1)." (PMID 22937035, 2012). "Midkine negatively correlated with tumor size (r = 0.40, p = 0.017), while it tended to positively correlate with its serum levels (r = 0.45, p = 0.081)." (PMID 22562257, 2012). "Midkine has been well documented to promote various activities related to oncogenesis and tumour progression, including cell migration, angiogenic functions, mitogenesis, and antiapoptosis." (PMID 18682710, 2008). "We demonstrated an anti-tumor effect of Ad5MK on midkine-positive tumor cells in vivo as well as in vitro." (PMID 18717994, 2008). "While MDK has long been recognized for its roles in cell survival, proliferation, and angiogenesis, new evidence highlights its ability to reprogram the tumor microenvironment by recruiting myeloid-derived suppressor cells, impairing T cell activation, and disrupting antigen presentation." (PMID 42004035, 2026). "And the tumor promotion effect of CAFs may be executed by BGN/MDK axis, which also reduced CD8+ T cell infiltration in TME." (PMID 41833003, 2026). "Similarly, GSVA enrichment scores for the MDK-NCL pathway were also markedly elevated in tumor samples." (PMID 40396179, 2025). "In the intracranial glioma model, blocking MDK signaling pathway could inhibit macrophage polarization towards the M2 phenotype and tumor malignant progression." (PMID 40527884, 2025). "Additionally, a recent study revealed that MDK rewires tumor-infiltrating T cells to secrete chemokines contributing to protumorigenic microenvironment." (PMID 40835683, 2025). "We evaluated the effect of MDK suppression on tumor growth in vivo." (PMID 40620228, 2025). "This may be due to the fact that CD68+ is a marker for macrophages in general, whereas the increased infiltration in MDK+ tumors may be predominantly tumor-promoting M2 polarized macrophages." (PMID 40429950, 2025). "SSC and ABS populations in LST-G exhibit significantly higher expression of MDK, which may possess certain tumor-promoting effects." (PMID 41018078, 2025). "The combined use of MDK inhibitors can significantly enhance the anti-tumor activity of IFN-γ." (PMID 40527884, 2025). "By enhancing the production of VEGF and other angiogenic mediators, MDK may worsen prognosis and facilitate tumor progression." (PMID 40500394, 2025).
tumor (continued). "This interaction was seen even in early colorectal cancer cases, suggesting that MDK may play a role in establishing the tumor microenvironment." (PMID 40429950, 2025). "Additionally, we have discovered a dominant MDK isoform with evidence for selection pressure towards its expression along with an increase in tumor grade." (PMID 40835683, 2025). "It has been hypothesized that MDK drives tumor growth via an autocrine mechanism, while concurrently promoting endothelial cell proliferation through paracrine signaling—an idea supported by the observation that MDK is primarily expressed in tumor cells." (PMID 40500394, 2025). "However, the published studies employed a limited number of tumor samples that limit MDK’s potential as a biomarker." (PMID 40429950, 2025). "We also drew a hierarchical diagram showing the autocrine and paracrine interactions among all cells in the MDK signaling pathway, thereby understanding that the C0 subtype is an important signal transduction transmitter, and tumor cells are its main receptors." (PMID 40616092, 2025). "Finally, in vitro knockdown of FAM49B validated its role in regulating MDK expression and shaping an immunosuppressive tumor microenvironment." (PMID 41246334, 2025). "The lack of an effect may be due to a more complex, indirect role of MDK in immunosuppression, as studies suggest it rewires the tumor microenvironment (TME) by modulating the myeloid compartment." (PMID 39908652, 2025). "Taken together, these data firmly establish MIF and MDK as abundantly secreted, tumor-derived immunosuppressive factors which may hamper cytotoxic function of T/NK cells inside and outside the TME." (PMID 39908652, 2025). "Similarly, MUC5AC+ tumor cells establish connections with other cells via the MDK-NCL receptor-ligand pair." (PMID 40124374, 2025). "Overall, our findings suggest that high MDK-NCL expression may predict poor ICI response by fostering an immune-excluded tumor microenvironment." (PMID 40396179, 2025). "Similarly, MDK-NCL also has the potential to influence tumor progression; however, its role and mechanisms have been underexplored in this context." (PMID 40036264, 2025). "For EGFRvIII(+) GBM patient single-cell data, the pattern analysis results showed that in the outgoing pattern analysis, tumor cells dominated Pattern3, with the MDK signaling pathway being the most active in Pattern3, followed by the PTN and SPP1 signaling pathways." (PMID 40527884, 2025). "Notably, while several of the tMDK forms are found in neoplasms, VA-MDK can be found in significant quantities alongside conventional MDK in human tissues, though its biological significance remains to be clarified." (PMID 40429950, 2025). "Prior research has indicated that MDK is essential in the development and occurrence of tumours." (PMID 40468625, 2025). "This enrichment suggests that MDK-NCL may serve as a defensive mechanism for tumor cells at immune hotspots, preventing effective immune cell infiltration and cytotoxic activity." (PMID 40396179, 2025). "Our observations further indicate that Tip-like ECs may actively respond to PARs signaling cues from Malignant Cluster01 tumor cells, particularly serving as receivers via the MDK-(ITGA6+ITGB1) ligand-receptor pairs." (PMID 39944338, 2025). "Moreover, MDK overexpression promoted the formation of lung metastases, indicating that MDK can promote tumour growth in the xenograft model, which is consistent with previous reports." (PMID 40468625, 2025). "Notably, the ligand-receptor pair MDK - NCL emerged as a highly enriched interaction in tumor cell communication." (PMID 40036264, 2025). "Finally, modulation of haemostasis-related factors such as MDK and TACSTD2 further inhibited angiogenesis and tumour-associated signalling." (PMID 41516237, 2025).
tumor (continued). "Overall, the immune microenvironment, angiogenesis, and stromal cell-tumor cell interactions collectively contribute to the aggressive nature and therapy resistance of HB, highlighting potential therapeutic targets such as midkine inhibition and TAM reprogramming." (PMID 40136353, 2025). "Another putative role for MDK is mediating communication within the tumor and its microenvironment." (PMID 40429950, 2025). "In addition, our research demonstrates that MDK influences tumour progression by regulating the Wnt/β‐catenin signalling pathway." (PMID 40468625, 2025). "The results showed that compared with the control group, the volume of GBM in the MDK overexpression group was larger, while the tumor growth in the MDK overexpression plus iMDK combined application group was slow, which was also supported by HE staining results." (PMID 40527884, 2025). "Notably, we found that PGA3+ tumor cells engage with other cell types through the MDK-NCL receptor-ligand pair." (PMID 40124374, 2025). "Additionally, the Midkine–Nucleolin (MDK-NCL) signaling axis has been recognized as a critical mediator of communication between tumor and immune cells." (PMID 41246334, 2025). "Across both tumor clusters, MDK–(ITGA4+ITGB1) and MIF–(CD74+CXCR4) emerged as prominent axes." (PMID 40948762, 2025). "Therefore, studying the changes in the expression of these proteins is essential to investigate the effect of MDK on tumour progression." (PMID 40468625, 2025). "This would suggest that MDK’s ability to influence the tumor microenvironment may support tumor survival beyond strictly reducing immune-mediated killing of cancer cells." (PMID 40429950, 2025). "Future studies evaluating MDK blood levels and their correlation with prognosis may further validate its utility as a tumor biomarker." (PMID 40500394, 2025). "Furthermore, MDK promotes tumor formation and growth, and increases the number of lymph node metastases." (PMID 40429950, 2025). "Additionally, Midkine (MDK) released from tumour cells interacted with SDC4, SDC1, NCL, ITGA4, ITGA6 and ITGB1 on immune cluster." (PMID 39187937, 2024). "Notably, all three tumor cell types were found to bind to other cell types via MDK-NCL receptor-ligand pairs." (PMID 38913193, 2024). "Lastly, the study showed a decrease in MDK levels in 36 patients after tumor resection, followed by an elevation at the time of tumor recurrence, further supporting the notion that MDK could be a potent biomarker for disease progression monitoring as well." (PMID 38247828, 2024). "Also, mice injected with MDK-knockdown cells had a higher number of tumor foci on the surface of the liver, further verifying previous findings." (PMID 38247828, 2024). "Although serum MDK levels did not exhibit correlations with tumor aggressiveness indicators, such as poor differentiation, microvascular invasion, larger tumor size, advanced tumor stage, survival, and tumor recurrence, they did correlate with MDK expression in tumor tissues." (PMID 38247828, 2024). "Indeed, the findings in 100 patients diagnosed with HCC showed that MDK was higher in tumor sizes exceeding 5 cm compared with those with sizes below 3 cm." (PMID 38247828, 2024). "However, we found that the MDK-NCL pair was specifically activated in the interactions between the CDK1/tumor cluster cells and other cell types, especially tumor cells, fibroblasts, and CDK1/stroma cluster cells." (PMID 36950551, 2023). "However, midkine inhibition apparently increased the cytotoxicity of sorafenib, with reduced tumor growth, volume and weight." (PMID 36906597, 2023). "Furthermore, we will review existing therapeutic strategies targeting MDK in neoplastic diseases and discuss the therapeutic value of MDK for the treatment of CNS disorders." (PMID 38098484, 2023).